CLCC1 (chloride channel CLIC like 1)
Description:
Anion-selective channel with Ca(2+)-dependent and voltage-independent gating. Permeable to small monovalent anions with selectivity for bromide > chloride > nitrate > fluoride (By similarity). Operates in the endoplasmic reticulum (ER) membrane where it mediates chloride efflux to compensate for the loss of positive charges from the ER lumen upon Ca(2+) release. Contributes to the maintenance of ER Ca(2+) pools and activation of unfolded protein response to prevent accumulation of misfolded proteins in the ER lumen. Particularly involved in ER homeostasis mechanisms underlying motor neurons and retinal photoreceptors survival (By similarity).
Synonyms: ERAC1; MCLC; RP32
Tractability: Antibody: UniProt predicts a signal peptide or a membrane-spanning region. PROTAC: ubiquitination databases record sites on it; its protein half-life has been measured.
Safety:
Unwanted effects reported when the protein is acted on. In parentheses: how it was acted on, where the effect was seen, and who reports it.
nausea and vomiting (source: ClinPGx)
Gene: Protein-coding gene on chromosome 1 (108,881,885 to 108,963,527, reverse strand). Ensembl gene ENSG00000121940.
Subcellular location: Endoplasmic reticulum membrane
Subcellular location (Human Protein Atlas): Endoplasmic reticulum
Gene Ontology:
Molecular function: chloride channel activity; protein binding; identical protein binding
Biological process: endoplasmic reticulum calcium ion homeostasis; chloride transmembrane transport
Cellular component: endoplasmic reticulum; endoplasmic reticulum membrane; membrane; mitochondria-associated endoplasmic reticulum membrane contact site
Genetic constraint (gnomAD): Loss-of-function variants: 28 observed, 49.36 expected, observed/expected ratio (o/e) 0.57, 90% interval 0.42 to 0.78. The upper end of that interval is the gene's LOEUF score, 0.78, which puts it in group 3 of 6, group 1 being the genes least tolerant of losing a copy. Missense variants: 462 observed, 598.33 expected, observed/expected ratio (o/e) 0.77, 90% interval 0.71 to 0.83. Synonymous variants: 193 observed, 220.1 expected, observed/expected ratio (o/e) 0.88, 90% interval 0.78 to 0.99.
Homologues: Orthologues: chimpanzee CLCC1 (99% identical), macaque CLCC1 (96% identical), rabbit CLCC1 (81% identical), dog CLCC1 (80% identical), pig CLCC1 (79% identical), guinea pig CLCC1 (77% identical), mouse Clcc1 (73% identical), rat Clcc1 (73% identical), tropical clawed frog clcc1 (40% identical).
Diseases named in the same sentence as CLCC1 in open-access papers:
CLCC1 is named in the same sentence as 24 diseases in open-access papers, as found by Europe PMC text mining. Sharing a sentence is not in itself a finding about the gene and the disease. The quoted sentences say what the papers report.
autosomal recessive retinitis pigmentosa (3 papers, 2008 to 2022). Autosomal recessive retinitis pigmentosa (RP) is an autosomally recessive inherited retinal dystrophy leading to progressive loss of the photoreceptors and retinal pigment epithelium and resulting in blindness usually after several decades. "We identified a homozygous missense alteration (c.75C>A, p.D25E) in CLCC1, encoding a presumptive intracellular chloride channel highly expressed in the retina, associated with autosomal recessive retinitis pigmentosa (arRP) in eight consanguineous families of Pakistani descent." (PMID 30157172, 2018).
amyotrophic lateral sclerosis (2 papers, 2023 to 2024). Amyotrophic lateral sclerosis (ALS) is a neurodegenerative disease characterized by progressive muscular paralysis reflecting degeneration of motor neurons in the primary motor cortex, corticospinal tracts, brainstem and spinal cord. "We identified CLCC1 rare variants in a Chinese amyotrophic lateral sclerosis (ALS) cohort." (PMID 37142673, 2023). "Here, we link rare variants of Chloride Channel CLIC Like 1 (CLCC1) to amyotrophic lateral sclerosis (ALS)-like pathologies." (PMID 37142673, 2023).
retinal degeneration (2 papers, 2008 to 2018). Degeneration of the retina. "Elucidating the pathophysiology of CLCC1 in arRP promises to provide insight into its biological role in retinal development and homeostasis, as well as the mechanisms underlying retinal degeneration." (PMID 30157172, 2018). "This may be consistent with greater sensitivity of retinal cells to decreases in CLCC1 function causing isolated retinal degeneration." (PMID 30157172, 2018). "In addition, high levels of CLCC1 retinal expression and especially in the photoreceptors and RPE, are consistent with CLCC1 mutation causing a retinal degeneration as is the finding that knocking out CLC3, another endosomal chloride channel, results in degeneration of the retina and hippocampus." (PMID 30157172, 2018).
retinitis pigmentosa (2 papers, 2022 to 2023). Retinitis pigmentosa (RP) is an inherited retinal dystrophy leading to progressive loss of the photoreceptors and retinal pigment epithelium and resulting in blindness usually after several decades. "Because CLCC1 D25E mutation has been associated with retinitis pigmentosa, we took D25E into account." (PMID 37142673, 2023). "CLCC1 is ubiquitously expressed, and knockout models of this gene in zebrafish and mice are lethal in the embryonic period, suggesting that possible retinitis pigmentosa mutations in this gene might be limited to those leaving partial activity." (PMID 35391798, 2022). "In agreement with this hypothesis, the mutation is the only CLCC1 mutation associated with retinitis pigmentosa to date, and all identified patients with this mutation share a common SNP haplotype surrounding the mutation, suggesting a common founder." (PMID 35391798, 2022).
channelopathy (1 paper, 2023). Channelopathies are a group of diseases caused by the dysfunction of ion channel subunits or their interacting proteins. "Therefore, further exploration of molecular pathways underlying mutant and WT CLCC1 protein degradation will provide important insights into the channelopathy mechanisms." (PMID 37142673, 2023). "Similar to CLCC1 rare variations dominant in ALS, 10% of K298A heterozygous mice developed ALS-like symptoms, pointing to a mechanism of channelopathy dominant-negatively induced by a loss-of-function mutation." (PMID 37142673, 2023).
cognitive decline (1 paper, 2024). "The clinical characteristics of CLCC1‐related patients included spinal onset, relatively rapid progression, and possible cognitive decline." (PMID 37916886, 2024).
hepatoma (1 paper, 2026). "Loss of CLCC1 resulted in the buildup of large lipid droplets in hepatoma cells and Clcc1 knockout in mice caused liver steatosis." (PMID 41741636, 2026).
idiopathic inflammatory myopathies (1 paper, 2023). "These were CLCC1 whose loss yields muscle myotonia, HLA-A/B that disappears during myogenesis and is linked as a risk factor for idiopathic inflammatory myopathies, and SMAD2 that shuts down myoblast fusion." (PMID 36282542, 2023).
insulin dependent diabetes mellitus (1 paper, 2013). "STXBP3 and CLCC1 genes on chromosome 1 have been linked to insulin dependent diabetes mellitus." (PMID 23741398, 2013).
lung adenocarcinoma (1 paper, 2022). A carcinoma that arises from the lung and is characterized by the presence of malignant glandular epithelial cells. "None of the PAMs have previously been detected in similar KRASG12D-driven mouse lung adenocarcinoma models, and Clcc1 was the only gene recurrently mutated in our cohort (p.A401V in 5498V, p.D449Efs*22 in 5522A)." (PMID 34779486, 2022). "However, non-synonymous mutations in KDM1A in human lung adenocarcinoma are as rare (0.53% in TCGA PanCancer Atlas) as CLCC1, suggesting that CLCC1 and KDM1A are not mutational drivers in this disease." (PMID 34779486, 2022).
lung squamous cell carcinoma (1 paper, 2023). "TMEM120B, HMOX2, CALCOCO2, LONP2, ZNF440, CLCC1, and CHMP3 were identified to be optimal prognostic factors for lung squamous cell carcinoma (LUSC)." (PMID 36999050, 2023).
Usher syndrome (1 paper, 2018). A syndromic diseae characterized by the association of sensorineural deafness (usually congenital) with retinitis pigmentosa and progressive vision loss. "The location of CLCC1 alongside GPSM2, which codes for the putative whirlin protein complex-interacting molecule, is interesting given the role of this complex in Usher syndrome." (PMID 30157172, 2018).
tumor (3 papers, 2022 to 2023). "For example, HMOX2 and CLCC1 have been characterized as biomarkers of tumor initiating cells, suppression of which will significantly increase cancer survival." (PMID 35768804, 2022). "Furthermore, significant differences in editing levels of chr17:46941503A > I of CALCOCO2, and chr1:109474650A > I of CLCC1 were observed between LUSC tumor tissues and normal tissues, indicating possible roles of these sites involving LUSC occurrence." (PMID 35768804, 2022). "In addition, the editing levels of CLCC1 chr1:109474650A > I (P = 0.004) and CALCOCO2 chr17:46941503A > I (P < 0.001) significantly differed between the tumor tissues and normal tissues." (PMID 35768804, 2022). "Interestingly, significantly negative correlations between chr12:122215052A > I level and TMEM120B expression, chr19:11945758A > I level and ZNF440 expression, chr1:109474650A > I level and CLCC1 expression, chr16:48388244A > I level and LONP2 expression, were observed in LUSC tumor tissues." (PMID 35768804, 2022).
neurodegenerative disease (1 paper, 2023). A disorder of the central nervous system characterized by gradual and progressive loss of neural tissue and neurologic function. "We link rare CLCC1 mutations to ALS and demonstrate that the ALS-associated mutations impair CLCC1 channel activity, damage ER ion homeostasis, and promote ER stress in the brain, implying that disruption of ER ion homeostasis maintained by CLCC1 underlies the etiology of neurodegenerative disease." (PMID 37142673, 2023).
CLCC1 also shares sentences with these, for which no sentence is quoted: cancer (2 papers); atherosclerosis (1); atrial fibrillation (1); autosomal dominant retinitis pigmentosa (1); Dystonia (1); infection (1); liver steatosis (1); motor neuron diseases (1); papilloma (1); peripheral nerve disease (1).